AQP9 (aquaporin 9)
Diseases named in the same sentence as AQP9 in open-access papers (continued):
Sharing a sentence is not in itself a finding about the gene and the disease.
steatosis (9 papers, 2013 to 2024). Increased lipid within the cytoplasm of cells. "Because AQP9 channel allows also passage of water, we verified whether the steatosis-associated down-regulation of AQP9 was also accompanied by a reduction of osmotic water transport in hepatocyte sinusoidal plasma membrane." (PMID 24205128, 2013). "In a cell model of NAFLD induced by oleic acid in LO2 cells, overexpression of AQP9 worsened steatosis, while silencing AQP9 reduced it." (PMID 39596202, 2024). "It is therefore conceivable that AQP9 increases early during onset of steatosis while decreases at a later stage of the disease, when fat accumulation becomes excessive." (PMID 30042691, 2018). "Reduction of HFD-induced steatosis was observed after decreasing the expression of liver Aqp9 by RNA interference." (PMID 24205128, 2013). "One possibility is that AQP9 increases during early steatosis whereas it decreases at a later stage when consistent and excessive steatosis has occurred." (PMID 24205128, 2013). "As a result, overexpression of AQP9 can induce steatosis in hepatocytes." (PMID 34659635, 2021). "Additionally, certain studies have suggested that AQP9 is involved in hepatocyte lipid metabolism and steatosis." (PMID 24959239, 2014). "The way AQP9 is handled in hepatosteatosis may vary depending on the origin, grade and histological pattern of steatosis." (PMID 24205128, 2013). "Furthermore, AQP9 is involved in the transformation of steatosis into chronic inflammation." (PMID 34659635, 2021). "Additionally, in a model of non-alcoholic fatty liver disease (NAFLD), AQP9 overexpression resulted in increased intracellular triglycerides, free fatty acids and glycerol levels, leading to the aggravation of steatosis, and this could be reversed with AQP9 suppression." (PMID 35187089, 2022). "Leptin-deficient mice, a murine model of NAFLD, displayed macrovesicular steatosis without changes in hepatic AQP9 mRNA and protein." (PMID 26159457, 2015). "Here, a low iodine diet reduced hepatic Aqp9 expression, and a lithogenic diet increased hepatic Aqp8 expression only in female but not male C57BL/6J mice which could protect the livers of female mice to hepato-steatosis and cholestasis." (PMID 36293210, 2022). "While selective small molecule AQP9 inhibitors with low micromolar IC50 values have already been reported and work is ongoing to increase the aqueous solubility of such blockers, preliminary studies using NAFLD cell models showed that silencing of AQP9 prevents or alleviates the degree of steatosis." (PMID 30042691, 2018).
astrocytoma (8 papers, 2013 to 2022). "On the contrary, AQP9 would promote astrocytoma cell invasion and motility 47 and its increase in mRNA-level was significantly correlated with aggressive progression and poor survival in clear cell renal cell carcinoma patients." (PMID 34475994, 2021). "AQP9 reduced the expression of E-cad and enhanced astrocytoma cell proliferation and migration through activating RAC serine/threonine protein kinase pathway." (PMID 31969493, 2020). "In brain tumors, the motility and invasion of astrocytoma cells can be suppressed by the down-regulation of AQP9, while the overexpression of AQP9 promotes the migration and invasion of astrocytoma cells." (PMID 33247170, 2020). "Reports of human expression of AQP9 are scarce and are limited mainly to pathological tissue, such as astrocytomas." (PMID 27420057, 2016). "In support of AQP9 expression in malignant glioma, another group found positive correlation between enhanced AQP9 expression and astrocytoma grade in immunoblots of astrocytoma tissue." (PMID 24086629, 2013). "AQP9 is the least studied of all AQP types in astrocytes; its localization in human brain has been unambiguously confirmed only in astrocytomas so far." (PMID 27420057, 2016).
clear cell renal cell carcinoma (8 papers, 2019 to 2026). "Similar to AQP1, AQP9 is upregulated in clear cell renal cell carcinoma (ccRCC) tissues compared to normal tissues, and upregulation of AQP9 can correlate with aggressive progression and poor survival in ccRCC patients." (PMID 36389709, 2022). "AQP9 up-regulation was detected in clear cell renal cell carcinoma specimens and was distinctly correlated to advanced clinicopathological factors and unfavorable survival outcomes." (PMID 35477402, 2022). "Metastasis is a primary driver of poor outcomes in clear cell renal cell carcinoma (ccRCC), yet the role of Aquaporin-9 (AQP9) in this process remains unclear." (PMID 42196217, 2026). "Furthermore, in renal clear cell carcinoma (KIRC), shorter survival was found in the AQP9 high expression group than in the low expression group." (PMID 36199571, 2022). "Since the potential connection between AQP9 and immune cells in the TME may be the key to its function, mIHC was performed on pathological specimens of renal clear cell carcinoma in order to further verify the possible relevance in clinical samples." (PMID 34804972, 2021).
type 2 diabetes mellitus (8 papers, 2015 to 2020). A type of diabetes mellitus that is characterized by insulin resistance or desensitization and increased blood glucose levels. "We aimed to investigate the associations between genetic variants in AQP7 and AQP9 genes and the risk of type 2 diabetes (T2DM) in Chinese population." (PMID 30598999, 2018). "AQP9 is down regulated by insulin in obese type 2 diabetes mellitus (T2DM) patients." (PMID 28635624, 2017). "This may explain why obese patients with type 2 diabetes (T2D) have decreased hepatic AQP9, compatible with a compensatory mechanism aimed at reducing the glycerol entry into hepatocytes and further enhancing the development of hyperglycemia." (PMID 26594198, 2015).
preeclampsia (7 papers, 2014 to 2025). Preeclampsia is a hypertensive disorder of pregnancy that is characterized by new-onset hypertension with proteinuria presenting after 20 weeks of gestation, and depending on mild or severe forms may initially present with severe headache, visual disturbances, and hyperreflexia. "Accordingly, we speculated that the increased oxidative stress observed in preeclampsia may impair AQP9 function as a lactate transporter." (PMID 34925067, 2021). "The activity and normal function of placental AQP9 are unknown, although, interestingly, AQP9 is also upregulated in preeclampsia, suggesting it may have a wider connection with intrauterine stress." (PMID 28615018, 2017). "Since feto-maternal water transfer is not altered in preeclampsia, the main role of AQP9 in human placenta is unclear." (PMID 34925067, 2021). "Given that preeclampsia is a syndrome of early placentation, we cannot discard that the abnormal expression of AQP3 and AQP9 observed at the end of gestation may be a consequence of a failure in the differentiation of the trophoblast stem cell." (PMID 30425647, 2018). "Considering that preeclampsia is related to an abnormal placentation and an altered placental expression of AQP3 and AQP9 was found after the onset of the maternal syndrome, we assumed that these proteins may participate in the early stages of placental development." (PMID 30425647, 2018). "Therefore, a non-functional AQP9 might be involved in the pathogenesis of preeclampsia." (PMID 34925067, 2021).
brain tumors (6 papers, 2010 to 2022). "Certain brain tumors were shown to upregulate AQP9 expression, and the putative increase in lactic acid permeability was assigned to severity." (PMID 35054513, 2022). "Robust expression of AQP9 in the cellular membrane has been observed in various brain tumors, and it was further proposed that the clearance of glycerol and lactate by AQP9 can alleviate lactic acidosis from high lactate-producing cancer cells." (PMID 35847914, 2022). "In addition, AQP9 serves essential roles during the progression of brain tumors." (PMID 31969493, 2020).
colitis (6 papers, 2008 to 2025). Inflammation of the colon. "Our experimental results validated the insights obtained from our bioinformatics analysis, indicating that AQP9 expression was elevated in the intestinal tissues of TNBS-induced colitis mice and decreased in the skin lesions of psoriasis mice." (PMID 40093802, 2025). "In comparison with the control group, AQP9 protein level was significantly elevated in the colonic tissues of TNBS-induced colitis mice, whereas it was markedly reduced in psoriatic skin lesions." (PMID 40093802, 2025). "Experimental assays in TNBS-induced colitis and imiquimod-induced psoriasis mice confirmed AQP9 expression via RT-PCR, Western blot and IHC." (PMID 40093802, 2025). "Three aquaporins (Aqp3, 8 and 11) were also repressed in TNBS colitis, whereas Aqp9 was upregulated." (PMID 18928539, 2008). "In the colitis mice, AQP9 protein level was significantly higher compared to the control group." (PMID 40093802, 2025). "In a mouse model of induced colitis with AQP9 knockout (AQP9-KO), the absence of AQP9 did not offer complete protection against colitis-associated inflammation but did diminish the DC-mediated inflammatory response." (PMID 37762642, 2023). "All together, our data indicate that AQP9 blockade can be an efficient strategy to reduce DCs inflammatory response but it is not sufficient to protect from acute inflammatory insults such as DSS induced colitis." (PMID 30386332, 2018). "With the intent to evaluate the importance of Aqp9 expression in a model of acute inflammation, we used 3% DSS to induce colitis in AQP9-KO and WT mice." (PMID 30386332, 2018). "In Aqp9 KO mice with induced colitis, AQP9 gating did not completely protect from colitis-related inflammation but reduced the inflammatory response of DCs." (PMID 35883453, 2022). "In AQP9-KO mice with induced colitis, AQP9 blockage did not completely protect from colitis-related inflammation but reduced DC inflammatory response." (PMID 33673336, 2021). "Despite the reduced release of inflammatory cytokines, Aqp9-KO mice were not protected from DSS induced colitis." (PMID 30386332, 2018). "Overall, our results suggest that AQP9 expression is among the steps needed for DCs maturation in response to an inflammatory stimulation even if it is not sufficient to protect from DSS induced colitis." (PMID 30386332, 2018).
gastric cancer (6 papers, 2018 to 2021). A primary or metastatic malignant neoplasm involving the stomach. "Nonetheless, AQP0, AQP6, and AQP8 mRNA expression with surgery alone and AQP9 mRNA with 5 FU chemotherapy were associated with significantly increased risk of low survival rate in gastric cancer patients." (PMID 29678898, 2018). "AQP9 expression could impact the prognosis of patients with different lymph node status in breast, lung and gastric cancers indicating that AQP9 expression can be associated with tumor metastasis." (PMID 33247170, 2020). "Additionally, AQP9 mRNA analysis showed that overexpression was linked with favorable OS in all gastric cancer patients including both intestinal and diffused type." (PMID 29678898, 2018). "Furthermore, both male and female gastric cancer patients presented with high AQP9 mRNA were also associated with longer survival rate especially in stages I and III." (PMID 29678898, 2018). "The results of the KEGG analysis illustrated the most significant pathways of genes co-expressed with AQP9 in breast, colon, lung and gastric cancers." (PMID 33247170, 2020). "The high AQP9 expression was also found to have better impact on the prognosis of patients at stage N0, N2 and N1+2+3 in gastric cancer." (PMID 33247170, 2020). "We found that immune related genes such as TLR8, Interleukin-7 (IL-7), Leptin (LEP), IL1RN had intimate relationships with AQP9 expression in breast, colon, lung and gastric cancers." (PMID 33247170, 2020). "In conclusion, the expression of AQP9 can make a profound difference to the prognosis of breast, lung and gastric cancers." (PMID 33247170, 2020). "Our results suggested that AQP9 expression had far-reaching effects in prognosis and immune cell infiltration in breast, colon, lung and gastric cancer patients." (PMID 33247170, 2020). "AQP9 mRNA expression was also associated with favorable OS in stage I gastric cancer patients, as well as it showed improved OS in stage III gastric cancer patients." (PMID 29678898, 2018). "We found that high expression of AQP9 and AQP11 mRNAs were associated with improved OS in male gastric cancer patients." (PMID 29678898, 2018). "Nonetheless, AQP9 mRNA expression and its role in gastric cancer remains to be clarified along with tumor marker and suppression characteristics." (PMID 29678898, 2018). "Taken together, while comparing gender outcomes, only AQP9 mRNA expression demonstrated longer OS in both male and female gastric cancer patients." (PMID 29678898, 2018). "In summary, we have identified a group of genes differentially regulated in the intestinal and diffuse histotypes of gastric cancers with AQP9, CARD14 and CXCR2 impacting on patients’ prognosis, although CXCR2 is the only factor independently impacting overall survival." (PMID 34012923, 2021). "However, overexpression of AQP9 was observed to have better impact on the prognosis in gastric cancer." (PMID 33247170, 2020). "Our findings in the study may throw new light on the significant role of AQP9 in breast, colon, lung and gastric cancers, as well as provide a new direction for further study of potential mechanisms between AQP9 and tumor-immune interactions." (PMID 33247170, 2020). "Intriguingly, AQP3 mRNA expression was associated with better OS with positive and negative HER2 in gastric cancer patients, whereas AQP9 and AQP10 mRNA levels were associated with better OS with negative HER2." (PMID 29678898, 2018). "Similarly, high expression of AQP3 and AQP9 mRNA revealed improved OS in female patients, whereas AQP0, AQP1, AQP6/2L and AQP8 were associated with poor OS in gastric cancer." (PMID 29678898, 2018). "Therefore, we can suppose that our results showing a worse prognosis for patients with high levels of AQP9 in intestinal gastric cancer subset, may be due to the presence of a stronger immune and inflammatory component." (PMID 34012923, 2021). "However, overexpression of AQP9 had a favorable prognosis in gastric cancer." (PMID 33247170, 2020).
gastric cancer (continued). "Therefore, positive AQP9 mRNA expression in gastric cancer can be a good prognostic marker." (PMID 29678898, 2018). "In which, we revealed AQP3, AQP9, and AQP11 mRNA expression were associated with improved OS in all gastric cancer patients especially with intestinal subtypes, whereas AQP0, AQP1, AQP4, AQP5, AQP6/2L AQP8, and AQP10 mRNA expression were associated with poor OS in all gastric cancer patients." (PMID 29678898, 2018). "It should also be addressed through molecular biology techniques to confirm whether AQP9 can be used as a therapeutic target in the immunotherapy of cancers and the specific mechanism in which AQP9 affects the prognosis and immune infiltrates in breast, colon, lung and gastric cancers." (PMID 33247170, 2020). "High hazard ratios for gastric cancer patients correlated with increased AQPs 2, 8 and 10 expression, contrasting with a reduced hazard ratio seen when AQP3 or AQP9 levels were increased." (PMID 32679804, 2020). "For these reasons, our results suggest that FPR2, CARD14, CXCR2, EFNA2, CXCR1, AQP9 TRIP13, along with GHRL and KLK11, could be used as promising biomarkers for gastric cancer diagnosis or prognostic evaluation." (PMID 34012923, 2021). "The present study suggests that targeting AQP9 and CXCR2 may represent a novel strategy for gastric cancer therapy, in intestinal and diffuse patients respectively." (PMID 34012923, 2021). "Additionally, AQP9 and AQP11 mRNA expression with negative HER2 was associated with longer survival rate in gastric cancer patients." (PMID 29678898, 2018). "In the present analysis, we revealed that AQP2, AQP6, AQP9, and AQP10 proteins were not expressed both in normal and gastric cancer tissues." (PMID 29678898, 2018).
Hyperglycemia (6 papers, 2012 to 2024). An increased concentration of glucose in the blood. "Hyperglycemia was shown to upregulate expression of AQP9, which in turn resulted in impaired steroidogenesis in Leydig cells through the oxidative stress pathway." (PMID 38338845, 2024). "AQP3 and AQP7 have been described to modulate glycerol efflux from adipose tissue, thus controlling the glycerol influx into hepatocytes, via AQP9 to prevent the excessive lipid accumulation and the subsequent aggravation of hyperglycemia." (PMID 33465153, 2021). "The liver-specific aquaporin protein AQP-9 could absorb excess glycerol and convert it into glycerol phosphate through glycerokinase, which is also one of the mechanisms leading to hyperglycemia." (PMID 37794517, 2023).
non-alcoholic fatty liver disease (6 papers, 2013 to 2024). "Moreover, with the increasing prevalence of non-alcoholic fatty liver disease, AQP9 is gaining attention as a therapeutic target in HCC due to its function as a water and glycerol channel." (PMID 39796114, 2024).
ovarian carcinoma (6 papers, 2018 to 2026). A malignant neoplasm originating from the surface ovarian epithelium. "Our results suggest that individual AQPs, except AQP2 and AQP9, are associated with unique prognostic significance and may thus act as new predictive prognostic indicators and potential drug therapeutic target in ovarian cancer." (PMID 29472315, 2018). "Overexpression of AQP9 was characteristic not only of normal ovarian superficial epithelium but also of malignant ovarian tumors." (PMID 33271827, 2020). "As with AQP9, high AQP5 expression was characteristic of malignant ovarian tumors associated with lymph node metastases." (PMID 33271827, 2020). "In the present study, our data revealed that AQP9 mRNA expression exhibited a null correlation with the prognosis in different histological types of ovarian cancer patients." (PMID 29472315, 2018). "Nevertheless, AQP9 expression showed less influence on the prognosis of ovarian cancer." (PMID 33247170, 2020). "Nevertheless, little is known about the prognostic value of AQP9 in ovarian cancer patients." (PMID 29472315, 2018). "Thus, the prognostic value of AQP2 and AQP9 in ovarian cancer needs further exploration." (PMID 29472315, 2018). "AQP6 and AQP9 were reported to be downregulated, whereas AQP8 was unchanged, in ovarian cancer, but their roles remain to be determined." (PMID 32679804, 2020). "In malignant forms of ovarian cancer, a much higher expression of AQP1, AQP5, AQP9 was observed compared to benign forms of ovarian cancer or normal ovaries." (PMID 33271827, 2020). "In the present study, constitutive expression of AQP2 and AQP9 mRNA showed not any correlation to the prognosis of all ovarian cancer patients, serous ovarian cancer patients, as well as endometrioid ovarian cancer patients." (PMID 29472315, 2018). "Higher expression of AQP9 was neither correlated with OS for all ovarian cancer HR = 0.91 (0.8–1.05), P=0.19 nor with serous, HR = 0.9 (0.77–1.05), P=0.18 and endometrioid cancer, HR = 0 (0–inf), P=0.076." (PMID 29472315, 2018).
melanoma (5 papers, 2010 to 2023). A malignant, usually aggressive tumor composed of atypical, neoplastic melanocytes. "In contrast, the overexpression of AQP9 in melanoma cells significantly increased the resistance to arsenite-induced apoptosis." (PMID 25410152, 2014). "Three proteins of this family (AQP1, AQP3, and AQP9) have probes that seem correlated with melanoma progression, all losing their expression in the process of going from normal skin to metastatic melanoma." (PMID 20805891, 2010). "The expression of AQP3, as well as AQP1, AQP5, and AQP9 seem to be correlated with melanoma progression, indicating a common pattern of downregulation from the higher values in normal skin and benign nevi." (PMID 20805891, 2010).